AFP (alpha fetoprotein)
Diseases named in the same sentence as AFP in open-access papers (continued):
Sharing a sentence is not in itself a finding about the gene and the disease.
tumor (continued). "Complete tumor necrosis was found in 26.1% (18 of 69) and 6.3% (2 of 32) of patients with an initial AFP under and over 100 ng/mL, respectively (p = 0.020)." (PMID 37568778, 2023). "The tumor markers, alpha-fetoprotein ([AFP], 5 ng/mL) and β-human chorionic gonadotrophin ([β-hCG], 0.88 ng/mL), were not elevated." (PMID 39516978, 2023). "Significant correlations emerged between FOXM1 expression and variables such as age, pathologic stage, tumor grade, vascular invasion, hepatic inflammation, and AFP levels." (PMID 37817774, 2023). "The results showed that grade, M, surgery (LR/LTD), radiation, chemotherapy, AFP, and tumor size significantly affected the OS of patients with intermediate/advanced HCC." (PMID 37576968, 2023). "Both AFP and EpCAM-positive circulating tumor cells have previously been described to be highly specific tumor markers." (PMID 38012205, 2023). "Both elevated preoperative AFP and CRP levels are linked to larger tumor diameter, a higher incidence of multifocal disease, microvascular invasion, and more advanced BCLC staging—all of which are recognized indicators of tumor aggressiveness (all P < 0.05)." (PMID 38053048, 2023). "The tumor cells were diffusely and strongly positive for AFP, and they exhibited hepatoid features with alveolar, acinar, or microcystic patterns." (PMID 37781207, 2023). "Based on the current literature, the overall survival and disease-free survival rates are influenced by factors such as AFP value, total tumor number, and total tumor diameter." (PMID 37909200, 2023). "Tumor micronecrosis improved the AUC of Milan criteria (0.77–0.79), the model for end-stage liver disease score (0.70–0.76), and serum alpha-fetoprotein (0.63–0.71) for the prediction of prognosis after liver transplantation." (PMID 36698095, 2023). "High levels of tumor markers, such as AFP, are used to determine the probability of a malignant tumor." (PMID 37915688, 2023). "The AFP was decreased from 2 500 μg/L to 5.5 μg/L;A significant reduction in tumor size;Liver transplantation was followed, but AR developed 6 d and died 10 d." (PMID 37545535, 2023). "They used the 1590 cm−1 peak of 4 MBA and the 1340 cm−1 peak of 4 NTP to quantitatively evaluate the concentration of PSA and AFP tumor markers, respectively." (PMID 37958586, 2023). "The use of tumour markers, such as AFP, and the number of required imaging modalities indicated remain uncertain." (PMID 37046636, 2023). "In hepatoblastomas, ctDNA was considered a more accurate indicator of disease severity and a better biomarker to track the dynamic tumor response compared to AFP." (PMID 37189699, 2023). "Alpha-fetoprotein (AFP) is the most commonly used tumor marker to diagnose HCC and it is also useful for prediction of survival and treatment response after local ablation." (PMID 36832184, 2023). "Before propensity matching, there were significant differences between patients treated with HAIC and AB, including the BCLC stage, Child–Pugh scores, serum AFP level, tumor size, portal vein invasion, and distant metastasis." (PMID 37686509, 2023). "On univariate analysis, we found that male sex, larger tumor size (≥5 cm), higher AFP level (≥400 ng/mL), and low PAD2 expression were potential candidates for multivariate analysis of survival (p < 0.05 on univariate analysis)." (PMID 36832148, 2023). "Tumor-derived AFP exhibits stronger immunosuppressive effects, characterized by lower dendritic cell maturation and decreased T cell activation." (PMID 37609076, 2023). "Larger tumour size (p < 0.001), raised Alpha Fetoprotein (AFP) level (p = 0.036) and higher Child–Pugh class (p = 0.008) were significantly associated with PVT." (PMID 37533945, 2023). "High NAP1L1 expression in HCC tissues is associated with aggressive clinicopathologic features, such as high serum AFP levels, tumor size, and tumor number." (PMID 36980210, 2023).
tumor (continued). "The same authors found that circulating EVs were also related to HCC size, being more sensitive than AFP for early tumor detection." (PMID 37686354, 2023). "The results of this study revealed that tumor diameter ≥10 cm, AFP ≥ 400 μg/L, MVI, Edmondson grade, PLT level, and satellite nodules were independent risk factors for postoperative OS and RFS, which were also confirmed by previous studies." (PMID 36540041, 2023). "Carfilzomib in combination with vascular endothelial growth factor receptor 2 (VEGFR2) blockade significantly prolonged survival by suppressing AFP-positive HCC growth in a subcutaneous tumor xenotransplantation model." (PMID 35955438, 2022). "In the multivariable Cox analysis, FAR (HR 1.211, 95% CI 1.014–1.445; p = 0.035) was shown as an independent predictive parameter of DFS, followed closely by HBsAg, AFP, CSPH, tumor size, BCLC stage and blood loss." (PMID 35606690, 2022). "It is well known that alpha-fetoprotein (AFP) was the clinically important tumor marker for HCC diagnosis and prognosis." (PMID 35311113, 2022). "The serum levels of classical tumor markers beta-human chorionic gonadotropin (bHCG), alpha-fetoprotein (AFP) and lactate dehydrogenase (LDH) have been shown to be significantly higher in NSGCTs than in SGCTs." (PMID 35465311, 2022). "But cirrhotic liver was also a feature among the second subgroup of patients, that presented with smaller tumours and lower AFP." (PMID 35497085, 2022). "The high expression level of RAE1 was correlated with T stage, pathologic stage, tumor status, histologic grade, and alpha-fetoprotein level." (PMID 35751040, 2022). "This mALF score showed the best c-index for predicting prognosis for OS and RFS among other AFP as a tumor factor and mALBI as an hepatic function index." (PMID 36358711, 2022). "Linear regression revealed that miR-675 expression was a significantly higher positive predictor than lncRNA-H19 for tumor size, pathologic grade, and AFP level; similarly, for cyclin D1 and VEGF protein expression." (PMID 36671388, 2022). "For factors including age, year of diagnosis, sex, race, grade, tumor size, AFP, and fibrosis score, propensity score matching was performed to eliminate the imbalance of baseline features and selection bias during groups." (PMID 36479067, 2022). "Tumor biology has to be assessed by tumor burden, AFP levels, and response to therapy, including the use of PET and/or tumor biopsy in selected cases." (PMID 35529597, 2022). "Long tumor diameter, poor BCLC stage, positive HBsAg, HCV, elevated creatinine, and high T-bilirubin were associated with poor OS in rHCC-C, and AFP >92 ng/mL was associated with poor OS in rHCC-C." (PMID 35342424, 2022). "The differences of SEA-SE8 and SEA-SE37 between subgroups of age, sex, AFP level, Child-Pugh grade, tumor type, tumor size, BCLC stage, and TNM stage were compared." (PMID 35747812, 2022). "Diagnostic power in predicting GPC3-positive HCC was highest for the combination of tomoelastography-quantified tumor stiffness and serum marker AFP." (PMID 36518314, 2022). "Preoperative serum AFP level is normally used as an indicator of tumour burden and an predictor of the prognosis of HCC after hepatectomy." (PMID 36100893, 2022). "Similar to the clinically established tumor markers for HCC AFP and GPC-3, NOPE is highly expressed during fetal liver development but is undetectable in healthy adult hepatocytes." (PMID 35246597, 2022). "Recently, several studies have identified optimized TCRs that can recognize AFP/HLA-A*02+ tumor cells." (PMID 35002508, 2022). "Alpha-fetoprotein (AFP) level, tumor maximal diameter, histological grade, micro-vascular invasion (MVI), RFS, and OS were significantly different between the control and PVTT groups." (PMID 36203429, 2022). "Clinical characteristics, imaging findings, and tumor markers such as α-fetoprotein (AFP) and β-human chorionic gonadotropin (HCG) were used as clinical variables." (PMID 35130327, 2022).
tumor (continued). "In this study, we demonstrated that male gender, higher AFP (≥400 ng/mL), larger tumor size (≥5 cm), multiple tumors, macrovascular invasion and extrahepatic metastasis were independent factors associated with poorer OS." (PMID 36423180, 2022). "In the univariate analysis, sex, smoking, HBsAg, ALT, AST, ALP, GLR, AFP, vascular invasion, blooding volume, allogeneic blood, TNM and tumor size were significantly associated with the recurrence of HCC with staging I–II." (PMID 35395799, 2022). "Serum tumor markers such as AFP, CEA, CA-199, CA-125, CA-153, and CA-50 have been applied in cancer diagnosis and monitoring." (PMID 35710379, 2022). "The serum levels of the tumor markers alpha-fetoprotein (AFP), carcinoembryonic antigen (CEA), carbohydrate antigen 19-9 (CA19-9), and cancer antigen 125 (CA125) were all within the normal range." (PMID 36324566, 2022). "The NLR is usually selected as a biological marker, not alone but rather in combination with other factors, such as the tumor size and number, and AFP or PIVKA-II levels." (PMID 35053580, 2022). "Serum alpha-fetoprotein levels returned to the normal range, and the tumor was undetectable after four courses of capecitabine and oxaliplatin therapy." (PMID 36051651, 2022). "Consistent with the results which were obtained from the TCGA database, we found that the expression of DDX56 was correlated with tumor size (P = 0.0341), AFP levels (P = 0.0486), and HBV positivity (P = 0.0496);." (PMID 36168636, 2022). "AFP is not only a tumor marker of HCC, but also a marker of the induction of hepatic progenitor cells." (PMID 35020772, 2022). "The high expression level of RAE1 was significantly correlated with T stage (P < 0.001), pathologic stage (P < 0.001), tumor status (P = 0.012), histologic grade (P < 0.001), and alpha-fetoprotein (AFP) level (P < 0.001)." (PMID 35751040, 2022). "It has been reported that circRNA profiles were related to HCC tumor size, serum AFP, and survival, suggesting circRNAs as biomarkers for HCC diagnosis and prognosis." (PMID 35264957, 2022). "Comparing a model of conventional tumor biomarkers including AFP and CA199, the nomogram showed a better distinction between ICC and HCC." (PMID 35480111, 2022). "It is common practice to use serum AFP as a predictive biomarker for HCC and is generally associated with the size of the tumour." (PMID 36013482, 2022). "Upon univariate analysis, seven factors (race, marital status, tumor size, histological grade, T stage, N stage and AFP level) were significantly related to extrahepatic metastasis." (PMID 36127436, 2022). "On diagnostic work-up, aspartate transferase, alanine transaminase, gamma-glutamyl transferase, alkaline phosphatase, bilirubin and serological tumor markers (carcinoembryonic antigen, carbohydrate antigen 19-9, and alpha-fetoprotein) were unremarkable." (PMID 35810683, 2022). "These were the AFP, albumin, tumor diameter, vascular invasion, PLR, RDW-CV, and RDW-SD, respectively." (PMID 36005195, 2022). "Blood-based tumor biomarkers have been developed in many cancers for screening and monitoring the tumor, such as alpha-fetoprotein in hepatocellular carcinoma, carcinoembryonic antigen in colorectal cancer, and prostate-specific antigen in prostate cancer." (PMID 35321426, 2022). "In univariate analysis, age, AFP, maximum tumor size, portal vein invasion, satellite nodules, tumor capsule formation, and TNM stage were strongly associated with disease-free and overall survival in HCC patients." (PMID 35729607, 2022). "In conclusion, the anticancer effects of 1,8-cineole and ellagic acid were demonstrated for the first time through 1) Conserving of liver functions 2) Lessening of HCC tumor markers; alpha-fetoprotein, ferritin, arginase-1, and alpha-L-fucosidase." (PMID 35081125, 2022).
tumor (continued). "The independent risk factors for HCC-related death after liver transplantation were AFP stage, tumor numbers, and maximal tumor diameter, which are consistent with the previous studies." (PMID 35936699, 2022). "Elevated tumor markers, especially α-fetoprotein (AFP), are considered prognostic markers for poor clinical outcomes among patients with HCC." (PMID 35804984, 2022). "Chi-square test analysis showed that downregulation of CFHR3 was positively relevant to elevated level alpha-fetoprotein (AFP), high histological grade, large tumor, HCC recurrence as well as advanced TNM stage." (PMID 35852862, 2022). "Our model was composed of four routine laboratory parameters (tumor size, tumor number, histological grade, and AFP), and it demonstrated superior delineation properties in terms of MVI diagnosis." (PMID 36684226, 2022). "The combo-MORAL score includes preoperative NLR ≥ 5, maximum AFP > 200 ng/mL along with tumor differentiation, vascular invasion, and tumor number and size and has excellent recurrence prediction (AUROC 0.91) though has not yet been validated." (PMID 35142988, 2022). "For HCC recurrence after treatment (for both surgical resection and liver transplant), tumor size and number, vascular invasion, alpha-fetoprotein (AFP) and neutrophil to lymphocyte ratio (NLR) are all components of HCC recurrence risk models." (PMID 35142988, 2022). "While higher AFP level (> 400 ng/mL), large maximum tumour diameter (> 3 cm), and portal vein thrombus were more frequently in patients with low PMI." (PMID 35639492, 2022). "We identified a VOC for diagnosis of early HCC and the VOCs that had a better sensitivity than serum tumor marker AFP for diagnosis of early HCC." (PMID 35351916, 2022). "The number of intrahepatic tumor lesions and median level of alpha-fetoprotein (AFP) level at diagnosis were comparable between the groups." (PMID 35159035, 2022). "The results showed that the prediction of prognosis based on DLGAP4 expression level was better than that based on traditional methods, such as AFP, pathological stage, T stage, M stage, tumour status, residual tumour, age, and sex." (PMID 36396671, 2022). "After PSM, the univariate analysis showed that PVTT invasion, tumor number, treatment modality, AFP, and TBIL were prognostic factors for OS (P < 0.05)." (PMID 36249011, 2022). "The prognostic implications of the expression patterns of three tumor markers, AFP, AFP-L3, and PIVKA-II, have been evaluated in patients with HCC." (PMID 35271670, 2022). "Statistical analysis showed that more HCC patients in the high GBA expression group than in the low GBA expression group showed high preoperative serum AFP levels (0.01 < P < 0.05) and high tumor grades (P < 0.01)." (PMID 36123535, 2022). "To further confirm the conjecture, we managed to find the correlation between down-regulated DEGs and T stage, pathologic stage, histological grade, AFP, vascular invasion, tumor status, PT, and race." (PMID 36685860, 2022). "In this study, comparing serum AFP levels between the tumour subtypes showed that the normal-like subtype showed trend with higher AFP serum levels compared to the proliferative." (PMID 36345011, 2022). "Tumor biomarker AFP, AFP-L3, α-L fucosidase, and abnormal prothrombin were collected to assist the definition of tumor progression or recession." (PMID 35800233, 2022). "Univariate COX regression analysis showed that age, race, pathological grade, AJCC stages, tumor size, AFP, surgery, tumor size, and income were all statistically significant on prognosis (P < 0.05)." (PMID 35784933, 2022). "Laboratory data revealed elevated tumor marker values for alpha-feto-protein (AFP), lactate dehydrogenase (LDH), and Ca-125." (PMID 36118998, 2022).
tumor (continued). "Currently, only one HCC tumor biomarker, AFP (70-kDa-serum glycoprotein), is being used for HCC detection." (PMID 35965577, 2022). "This further indicates that tumor cells secret AFP into the serum, the detailed mechanism is still unclear." (PMID 35461226, 2022). "The cost-effectiveness of an alternative method for measuring tumor markers (e.g., longitudinal AFP measurement or concomitant use of multiple tumor markers) will require evaluation in future studies." (PMID 36112645, 2022). "Demographic and clinicopathological metrics were extracted, including age, sex, race, marital status, tumor size, histological grade, T stage, N stage, M stage, alpha-fetoprotein (AFP), and liver fibrosis score." (PMID 36127436, 2022). "These facts underscore the value of AFP as a surrogate marker for HCC tumor biology and for predicting HCC recurrence after liver transplantation." (PMID 35053580, 2022). "AFP assessment is important as detection of small tumours or metastases can at times be difficult on routine imagistic evaluation." (PMID 35497085, 2022). "E-S grade, serum AFP levels, tumor diameter, and multinodular fusion were significantly different between groups (p < 0.05)." (PMID 35402463, 2022). "Of the 23 patients who received hepatectomy after TACE as a down-staging therapy (DEB-TACE: 15, cTACE: 8), we collected the liver function indexes and the tumor markers AFP data before and after DEB-TACE at 1 month in these patients." (PMID 35941634, 2022). "Tumor markers that contribute to the diagnosis of HCC include AFP heterogeneity, Glypican-3, osteopontin, Des-γ-carboxyprothrombin, Golgi protein-73, abnormal pro-thrombin, and heat shock protein." (PMID 35854221, 2022). "Patients positive for VEGFR2 were confirmed to have higher serum AFP levels, larger tumor dimensions on ceMRI, higher LI-RADS scores, and larger tumor dimensions on final pathology (all p<0.001)." (PMID 36313714, 2022). "The parameters significantly associated with OS were HBV-DNA, HBeAg, AFP level, NEU concentration, LYM concentration, PLT concentration, AST level, GGT level, tumour diameter, histologic differentiation, MVI, satellite lesions, and type of hepatectomy." (PMID 36100893, 2022). "In a French cohort, when AFP levels were <100 ng/ml, only 2% of patients had a G3 tumor and only 20% of patients had mVI (plus 5% macroinvasion)." (PMID 35529597, 2022). "Clinical diagnosis of TGCTs relies on physical examination, testicular ultrasound and determination of specific tumor markers such as alpha feto protein (AFP), beta-hCG (β-hCG) and lactate dehydrogenase (LDH)." (PMID 34779884, 2022). "Pathologically, patients with AAR > 1.6 had more aggressive tumour characteristics, such as larger tumour size, higher incidence of microvascular invasion, and severe histologic activity, and higher AFP level than patients with AAR < 0.7." (PMID 35945520, 2022). "Similar significant associations were found between down-regulation of STAT5 expression and AFP level > 100 ng/ml (p = 0.006), vascular invasion (p = 0.009), and advanced tumor stage (p = 0.007)." (PMID 36374927, 2022). "Disease volume was similar in the high and low AFP group (tumour number 3 vs. 3 p = 0.49; size of recurrence 2.3 vs. 2.0 cm, p = 0.97), despite the huge difference in AFP (1128 vs. 7 ng/mL, p < 0.001)." (PMID 35956006, 2022). "Sorafenib provided longer survival than lenvatinib in patients> 60 years of age (HR = 1.84, 95% CI 1.01–3.36, p = 0.044), AFP ≤ 200 ng/mL (HR = 2.09, 95% CI 1.16–3.76, p = 0.012), and tumor size ≤ 5 cm (HR = 2.39, 95% CI 1.13–5.04, p = 0.019)." (PMID 35337274, 2022). "Conventional prognostic markers for HCC include alpha-fetal protein (AFP), tumor staging, and Barcelona Clinic Liver Cancer (BCLC) staging, but their performance is inconsistent." (PMID 35880030, 2022). "The reduction of AFP and tumor size after chemotherapy by 60% and 50%, respectively, has a direct correlation with prognosis." (PMID 35703678, 2022).